TNF (tumor necrosis factor)
Diseases named in the same sentence as TNF in open-access papers (continued):
Sharing a sentence is not in itself a finding about the gene and the disease.
glaucoma (continued). "Alterations in levels of various external factors including TGF‐β, endothelin‐1, connective tissue growth factor (CTGF), lysophosphatidic acid (LPA), TNF‐α, autotaxin and extracellular matrix in the AH of glaucoma patients have been found to be associated with elevated IOP in glaucoma patients." (PMID 35170203, 2022). "In our study, we aimed to find out associated factors to TNF-α elevation in glaucoma patients." (PMID 36079162, 2022). "Although it is reported that TNF-α could modulate outward K+ currents in RGCs, the mechanisms underlying TNF-α-induced hyperexcitability of RGCs in glaucoma are largely unknown." (PMID 34419081, 2021). "In conclusion, genetic variability in IL1B and IL6 may be associated with glaucoma risk, while GPX and TNF may be associated with the glaucoma phenotype." (PMID 33803434, 2021). "Inhibition or knockout of TNFα or C1q reduce experimental glaucoma loss of ganglion cells." (PMID 33529207, 2021). "Finally, polymorphisms of the TNFα gene were correlated with a higher incidence of OAG in a glaucoma patient population." (PMID 32106630, 2020). "Indeed, simple experiments neutralizing the actions of TNF were able to restore axon function and decrease the loss of RGCs in glaucoma." (PMID 32218163, 2020). "IL1A and TNF polymorphisms are associated with primary open angle glaucoma." (PMID 33147455, 2020). "However, chronic use of corticosteroids can cause cataracts and glaucoma while anti-TNFα antibodies can increase patients’ susceptibilities to infectious diseases, cancer, and other complications." (PMID 32708100, 2020). "The anti-inflammatory properties of iTRAB® were investigated in 3D-HTMCs through its ability to modulate the increase in pro-inflammatory (i.e., IL-1α, IL-1β, IL-6, and TNF-α) and pro-fibrotic cytokines, as well as MMPs which are known to be associated with glaucoma." (PMID 33172106, 2020). "Neuroinflammation and pro-inflammatory cytokines such as TNF-α have been implicated in glaucoma." (PMID 30673862, 2019). "In human and experimental glaucoma, multiple inflammatory pathways have been implicated in the pathogenesis of disease, including the Toll-like receptor signaling pathway, the inflammasome pathway, the TNFα pathway, and the complement cascade." (PMID 31570110, 2019). "TNF has been linked to optic nerve degeneration in glaucoma patients." (PMID 23316132, 2012). "In addition, TNFα polymorphisms have been associated with primary open angle glaucoma in Japanese and Chinese populations." (PMID 21479271, 2011). "Higher preoperative levels of TNF-α and IL-6 in aqueous humour may contribute to the development of inflammatory milieu and were associated with worse outcome of glaucoma surgery." (PMID 20467456, 2010). "This transition is considered to be an important enhancer of transcriptional activation associated with elevated levels of TNF-α, which have been shown to be involved in increased susceptibility to different eye diseases including diabetic retinopathy and glaucoma." (PMID 20029655, 2009). "Thus, while in a naïve optic nerve, sildenafil might induce damage, when there is glaucoma-associated neuropathy, the TNF pathway is activated, counterbalancing the glaucoma-induced damage." (PMID 37111243, 2023). "Therefore, vascular instability could be a contributing factor associated with TNF-α elevation that may cause glaucoma pathogenesis related to TNF-α." (PMID 36079162, 2022). "However, it is noteworthy that activation of TNFR2 expressed in Müller cells promoted the production of TNF-α and may cause positive feedback to aggravate neuroinflammation in glaucoma." (PMID 34419081, 2021). "Moreover, signaling pathways that are implicated in glaucoma, specifically responses to mechanical and ischemic stress, are known to be involved in the regulation of the inflammasome: TNFα, TLR4 receptors, MyD88, and NF-κB are essential parts of the transcriptional priming of the complex." (PMID 34440742, 2021).
glaucoma (continued). "Mutations in TNF-α might be involved in causing different neurodegenerative disorders, therefore it is important to consider it as a novel therapeutic target for the treatment of neurodegenerative diseases like glaucoma." (PMID 20029655, 2009). "For instance, deficiency of three proinflammatory cytokines, complement component 1, subcomponent q (C1q), interleukin 1 alpha (Il1a), and tumor necrosis factor (Tnf), resulted in significant protection of RGCs after glaucoma-relevant insults." (PMID 41728092, 2026). "The integrated system significantly reversed glaucoma-induced changes in TNF-α, IL-8, MYOC, NRF2, TIMP1, and IL-1β levels, resembling those of the healthy group." (PMID 40643885, 2026). "In this study, we detected elevated TNF levels in glaucoma patients and demonstrated that OPTN-E50K operates via RIP1 to regulate RGC death." (PMID 39448868, 2025). "In corneal chemical injury models, TNF-α blockade reduces monocyte infiltration into the retina and microglial activation, thereby decreasing the incidence of secondary glaucoma and RGC death." (PMID 41409280, 2025). "While neuroinflammation has been recognized as an important pathological factor in neurodegenerative diseases, tumor necrosis factor (TNF) has been suggested as a primary proinflammatory mediator in glaucoma." (PMID 39448868, 2025). "TNF-α regulates L- and T-type Ca2+ currents and modulates Ca2+ channel subunit expression, participating in the apoptosis of RGCs in glaucoma." (PMID 40486511, 2025). "CIH leads to increased retinal TNF-α, activating related pathways and triggering inflammatory responses that damage retinal ganglion cells, promoting glaucoma progression." (PMID 40486511, 2025). "On a molecular level, GBE targets various signalling pathways that play a role in glaucoma, such as the protein-1 signalling pathway, which suppresses tumour necrosis factor α (TNF α)." (PMID 39951447, 2025). "Activation of NF-κB, a key regulator of inflammation, is typically associated with the expression of proinflammatory cytokines, such as TNF-α and IL-1β, which exacerbate neuronal damage in glaucoma." (PMID 40970091, 2025). "TNF-α activates inflammatory cells, releases other inflammatory mediators, amplifies the inflammatory response, and drives the progression of glaucoma." (PMID 40486511, 2025). "TNF is a potent inflammatory agent in the pathology of glaucoma, and TNF-related necroptosis is promoted by the RIPK1/RIPK3 axis." (PMID 40345829, 2025). "It was previously reported that upregulated TNF and RIP3 levels in human glaucoma patient retinas are linked to neurodegeneration." (PMID 39448868, 2025). "Most likely other inflammatory cytokines are involved as well, especially IL-6 and IL-1β, but the role of TNF-α in glaucoma has been under strong suspicion for over two decades." (PMID 37803488, 2024). "The onset of the inflammatory process in glaucoma is triggered by impaired communication between RGCs and glial cells, inducing the release of proinflammatory mediators, such as ROS, NO, TNF-α, and IL-1β." (PMID 38333055, 2024). "Specifically, levels of TNF-α and its receptor appear higher in the optic nerve head of aged glaucoma patients, contributing to increased axonal neurodegeneration due to increased IOP in conjunction with increased age-related susceptibility." (PMID 38333055, 2024). "In the optic nerve of patients with glaucoma, elevated levels of both TNF-α and Fas ligand (FasL), a protein with proapoptotic capacity, are observed, and both are linked to the pathogenesis of glaucoma." (PMID 38333055, 2024). "In line with this, the present results show that in the MCE glaucoma model, there was an enhanced expression of both IL-6 and TNF-α, in accordance with previous findings." (PMID 38337691, 2024). "Inflammation also plays a significant role in glaucoma, with pro-inflammatory cytokines like tumor necrosis factor-alpha (TNF-α) being upregulated in the retina and optic nerve head." (PMID 39458902, 2024).
glaucoma (continued). "In fact, in human eyes with glaucoma, TNF-α, TNFR1, and TRADD are upregulated from protein samples, and active forms of caspases-3, -8, -9, and -12 are detected in RGCs." (PMID 39408817, 2024). "Inflammatory factors, such as TNF, IL-1β, IL-18 and MMP, can promote the death of RGCs, which is a hallmark of glaucoma development." (PMID 38437213, 2024). "In patients with primary open-angle glaucoma (POAG), many studies found that increased cytokines such as TGF-β2, TNF-α, MCP-1, or interleukin (IL)-8 were associated with higher IOP." (PMID 38920659, 2024). "Among the glia-produced proinflammatory cytokines that function as effectors of neuroinflammation, TNFα comes forward as a prominent contributor to the proinflammatory-to-anti-inflammatory cytokine imbalance in human glaucoma and experimental models." (PMID 38824526, 2024). "Although several studies have demonstrated the therapeutic effect of TNF inhibition for optic nerve injury and glaucoma, clinical studies evaluating the efficacy of TNF inhibitors for primary or secondary glaucoma remain limited." (PMID 39408817, 2024). "Glucagon-like peptide 1 receptor agonist reduced microglia activation and TNFα expression in glaucoma models." (PMID 37240082, 2023). "Growing evidence supports the role of TNF-α as a mediator of RGC death in glaucoma through the binding of TNF receptor-1 (TNF-R1)." (PMID 37242611, 2023). "Increases in TNF-alpha have been reported in the retina samples and optic nerve of glaucoma patients." (PMID 37511830, 2023). "We examined the EMT response of ARPE-19 cells to the following glaucoma-related stimuli: cyclic mechanical stretch, mechanical stiffness, transforming growth factor beta (TGFβ), and tumour necrosis factor alpha (TNFα)." (PMID 37048820, 2023). "Tumor necrosis factor alpha (TNFα)–mediated neuroinflammation is another proposed mechanism for glaucoma progression." (PMID 37111243, 2023). "TNF-alpha levels were higher in the glaucoma group compared to the control group (p < 0.05, unpaired t-test)." (PMID 37511830, 2023). "In a murine glaucoma model, the administration of etanercept has been shown to inhibit TNF-α signaling, leading to a reduction in glial activation and the preservation of RGCs." (PMID 37765001, 2023). "Rapamycin treatment was neuroprotective by downregulating caspase-3 expression and inhibited TNFα, ROS and NO expression in different glaucoma models." (PMID 37240082, 2023). "ELISAs have previously been used to detect the presence of TNF-alpha in glaucoma and cataract patients." (PMID 37511830, 2023). "Ko and co-workers recently demonstrated in an experimental neuroinflammatory model of glaucoma that TNF-α can exclusively induce necroptosis in axons." (PMID 37765001, 2023). "This is very interesting, as TGFβ levels are increased in the glaucomatous optic nerve, and TNFα levels increased in the retina in glaucoma." (PMID 37048820, 2023). "Increased levels of pro-fibrotic cytokines, notably transforming growth factor β (TGFβ) and tumor necrosis factor α (TNFα), have been implicated in ONH remodeling in glaucoma." (PMID 37048820, 2023). "For example, decreased glutamine synthetase required for glutamate recycling, increased production of TNFα (tumor necrosis factor α) and NO have been shown in glaucoma models." (PMID 38983043, 2023). "Microglial secretion of IL-1α, TNF-α, and C1q was increased in a mouse glaucoma model, suggesting the possibility that microglia induce A1 astrocytes resulting in RGC damage in glaucoma." (PMID 38983051, 2023). "TNF-alpha is released by these activated glial cells, contributing to the neuroinflammatory response in glaucoma." (PMID 37511830, 2023). "It has been demonstrated that elevated levels of the inflammatory cytokine tumor necrosis factor-alpha (TNF-α) can induce retinal ganglion cell (RGC) apoptosis in patients with glaucoma." (PMID 37511830, 2023).
glaucoma (continued). "In thissituation, it is expected that glaucoma can be accurately diagnosedusing substances such as inflammatory cytokines and TNF-α asbiomarkers." (PMID 37748126, 2023). "TNF-α levels are associated with IOP and vascular factors, indicating the potential role of TNF-α in glaucoma." (PMID 36079162, 2022). "Another critical activator of neuroinflammation in glaucoma is TNF-α, which is produced by astrocytes and especially microglia." (PMID 35778750, 2022). "Many other key inflammatory pathways are involved in the pathogenesis of glaucoma and are normal in human and animal models of glaucoma, for instance, toll-like receptor and TNF-α pathways, among others." (PMID 36741384, 2022). "AH derived from POAG patients has been shown to have elevated levels of TNF‐α,10 and TM tissue derived from glaucoma patients has been documented to exhibit reduced TM cell density." (PMID 35170203, 2022). "Tumor-necrosis-factor-alpha (TNFα) and interleukin-18 (IL-18) levels in AH were different between all three groups (glaucoma>POH>normal) (p = .05, p = .02, respectively)." (PMID 35998207, 2022). "Histological studies of human retina have shown intense inflammatory staining in the ONH of glaucoma eyes, increased protein levels of pro-inflammatory cytokines (TNF-α, IL-1β, IL-6, IL-8, and IFN-γ) and infiltration of CD163+ macrophages to the optic nerve." (PMID 35986368, 2022). "Caffeine, an unspecific A2AR antagonist, was neuroprotective, as it lowered intraocular pressure and reduced the activation of microglia and the inflammatory cytokines IL-1β and TNF-α in a mouse glaucoma model." (PMID 35387355, 2022). "Proinflammatory microglia/macrophages and neurotoxic astrocytes were the main source of proinflammatory cytokines such as TNF and IL-1β in the context of glaucoma." (PMID 35132339, 2022). "Currently, accumulating evidence supports the ligation of TNF to TNFRs in the glaucoma model, although the therapeutic roles of TNF antagonist mediated RGCs survival have yet to be explored." (PMID 35651608, 2022). "Elevated serum expression of TNF has been consistently observed in human glaucoma, and its overexpression somewhat shifted towards TNFR1 than TNFR2." (PMID 35651608, 2022). "TNF-α is elevated in the aqueous humor, retina and optic nerve of glaucoma patients as well as in a glaucoma mouse model induced by chronic ocular hypertension." (PMID 35844208, 2022). "Glial cell activation and TNF-α mediated cell death was a contributing mechanism in this glaucoma model." (PMID 36079162, 2022). "In the present study, we detected the formation of proinflammatory microglia/macrophages and neurotoxic astrocytes, deposition of complement C3, and production of proinflammatory cytokines (TNF and IL-1β) in the rat glaucoma model we previously used." (PMID 35132339, 2022). "Several inflammatory molecules that can influence the optic axon, such as tumour necrosis factor (TNF-α), nitric oxide, and vascular endothelial growth factor, are upregulated during glaucoma." (PMID 36012964, 2022). "One of the approaches that can be utilized for anti-TNF in glaucoma is developing pharmacological means with selectivity to TNFR1 or directly to TNFR2." (PMID 35651608, 2022). "Induction of these cells would initiate a number of inflammatory pathways, including TNF pathway, and drive neuroinflammation in glaucoma." (PMID 35651608, 2022). "This benefit potentially can be translated as a new therapeutic approach in glaucomatous patients since up-regulated TNF expression has also been implied in glaucoma patients and experimental animal models." (PMID 35651608, 2022). "The source of TNF-α in glaucoma is thought to be chronically reactive glial cells after injury such as high intraocular pressure, acute ischemia, and excitotoxicity." (PMID 36079162, 2022). "In glaucoma patients, TNF-α levels were increased in the optic nerve and the retina in glaucomatous eyes." (PMID 36079162, 2022).
glaucoma (continued). "TNF-α, a major immunomodulator and inflammatory cytokine, has been suggested to mediate the apoptotic death of retinal ganglion cells in glaucoma patients." (PMID 33803434, 2021). "Our results revealed a novel mechanism of TNF-α in glaucoma and provided a promising therapeutic target." (PMID 34419081, 2021). "SARM1 has also been found to be necessary for RGC axon loss and cell death, as well as oligodendrocyte loss in the optic nerve, in a neuroinflammatory D2 mouse model of glaucoma induced by intravitreal TNF–α injection." (PMID 34198948, 2021). "Similar to inflammatory responses in other neurodegenerative diseases or aging, microglia-derived IL1α, TNFα, and C1q can mediate the induction of proinflammatory and neurotoxic astrocytes in glaucoma." (PMID 34199494, 2021). "A proinflammatory cytokine imbalance in glaucoma is best exemplified by increased glial production of TNFα that functions as the amplifier of neurodegeneration and effector of RGC injury." (PMID 34199494, 2021). "Major proinflammatory cytokines secreted by glial cells in glaucoma, including TNFα or FasL are transcriptional targets for NF-κB." (PMID 34199494, 2021). "High levels of TNF-α in plasma and aqueous humor have been associated with POAG and PXG, and its potential as a biomarker for glaucoma diagnosis or progression has been suggested." (PMID 34575451, 2021). "In this sense, it has been described that apoptosis signal-regulating kinase 1 (ASK1) mediated apoptotic pathway acts by decreasing TNF-α signalling, which is a neurodegeneration mediator in glaucoma involved in the regulation of cytokine-induced apoptosis." (PMID 34575451, 2021). "Elevated levels of tumor necrosis factor alpha (TNF-α) can induce retinal ganglion cell (RGC) apoptosis in patients with glaucoma, and for this reason, its expression has been studied." (PMID 34575451, 2021). "Previous studies have demonstrated that TNF-α was involved in retinal axon loss and RGC death in glaucoma." (PMID 34419081, 2021). "Direct neutralization of soluble TNF-α in the retina of experimental glaucoma was able to reduce RGC death efficiently." (PMID 34419081, 2021). "Tumor necrosis factor-alpha (TNF-α) is a major pro-inflammatory cytokine released from activated retinal glial cells in glaucoma." (PMID 34419081, 2021). "Immune inflammatory response mediators like proteolytic enzymes and pro-inflammatory cytokines (TNF-α, IL-1β, IL-6, IL-12, and NO) have recently become a target of glaucoma research." (PMID 33803434, 2021). "In other retinal disorders like glaucoma or DR, minocycline also inhibits the release of the pro-inflammatory cytokines IL-1β, and TNF-α, the expression of PARP1, and photoreceptor cell death." (PMID 33672611, 2021). "Inhibition or genetic deletion of TNF-α reduces the activation of microglia, and the blockade of TNF-α signaling has been shown to protect RGCs in an experimental glaucoma mouse model." (PMID 33796062, 2021). "Retinal glial cells, when exposed to stressors simulating ischemia or ocular hypertension/glaucoma, upregulated and released TNFα." (PMID 32031578, 2020). "Intravitreal injections of TNFα in normotensive eyes of rabbits and mice induced axonal damage to the optic nerve comparable to that observed in glaucoma patients." (PMID 32106630, 2020). "Based on previous studies of glaucoma, TNF-α presents increased astroglial production in the glaucomatous human retina and optic nerve." (PMID 32859212, 2020). "Using a mouse model of glaucoma, we demonstrate that ocular hypertension is sufficient to trigger production of C1q, interleukin-1α (IL-1α), and tumor necrosis factor α (TNF-α), three cytokines necessary and sufficient to drive the formation of A1 astrocytes." (PMID 33147455, 2020).